HOXD10 (homeobox D10)
Diseases named in the same sentence as HOXD10 in open-access papers (continued):
Sharing a sentence is not in itself a finding about the gene and the disease.
endometrial cancer (3 papers, 2012 to 2021). Primary or metastatic malignant neoplasm involving the endometrium (mucous membrane that lines the endometrial cavity). "In conclusion, these results suggest that HOXD10 is one of the main targets through which miR-501 promotes tumor progression in endometrial cancer." (PMID 34022794, 2021). "Evidence of altered expression of HOXD10 is strong in breast and endometrial cancer, in which HOXD10 expression is progressively reduced in epithelial cells as malignancy increases." (PMID 22227861, 2012). "In conclusion, we found that miR-501 is overexpressed in CN-high endometrial cancer and proved that miR-501 could promote cell proliferation, invasion and migration in endometrial cancer through directly targeting the downstream target HOXD10." (PMID 34022794, 2021).
Ewing sarcoma (3 papers, 2017 to 2024). A small round cell tumor that lacks morphologic, immunohistochemical, and electron microscopic evidence of neuroectodermal differentiation. "Menin knockdown in multiple Ewing sarcoma cell lines also reduces the expression of HOXD13 and HOXD10, both of which are frequently overexpressed in Ewing sarcomas." (PMID 39336822, 2024). "We recently reported that high expression of posterior Homeobox D gene cluster (HOXD) genes is a hallmark of Ewing sarcoma and that ectopic expression of EWS-FLI1 in neural crest-derived MSCs hijacks normal epigenetic regulation of HOXD10, HOXD11, and HOXD13." (PMID 30845695, 2019). "Human Ewing sarcoma tumors over-express HOXD10, HOXD11, and HOXD13 and maintenance of the tumorigenic Ewing sarcoma state requires continued high-level expression of HOXD13." (PMID 30845695, 2019). "In the context of human Ewing sarcoma, knockdown of HOXD10, HOXD11, and HOXD13 all independently impaired the growth and invasive properties of tumor cells, demonstrating that despite the marked over-expression of HOXD13, all members of the posterior HOXD cluster contribute to human tumorigenesis." (PMID 30845695, 2019). "In addition, knockdown of HOXD13, and also of HOXD10 and HOXD11, results in loss of tumorigenicity, verifying the identity of posterior HOXD genes as critical oncogenes in Ewing sarcoma." (PMID 27888797, 2017). "HOXD10, HOXD11 and HOXD13 play essential roles in maintaining the oncogenic phenotype of Ewing sarcoma proliferation, invasion and metastasis (current study and Ref." (PMID 27888797, 2017). "We and others have shown that the posterior HOXD genes, HOXD9, HOXD10, HOXD11, and HOXD13 are overexpressed by Ewing sarcoma and that the promoters of these genes are devoid of the repressive H3K27me3 mark and highly enriched with the MLL-mediated H3K4me3 mark." (PMID 27888797, 2017).
lymph node metastasis (3 papers, 2017 to 2022). "Second, a larger study sample is needed to assess the relationship between HOXD10 and lymph node metastasis." (PMID 34825321, 2022). "Furthermore, HOXD10 hypermethylation was significantly more pronounced in cancer tissues with lymph node metastasis (p = 0.0120), suggesting that HOXD10 hypermethylation plays a key role in the development of CRC." (PMID 34790580, 2021). "Notably, the expression levels of HOXD10 were related to clinical stage (P < 0.05) but not to age, sex, lymph node metastasis, or pathological differentiation (P > 0.05)." (PMID 34825321, 2022).
neuroblastoma (3 papers, 2012 to 2020). Neuroblastoma (NB) is the most common solid, extracranial childhood tumor. "Elevated expression of HOXD genes including HOXD10 was reported to be associated with unfavourable prognosis and poor outcome in neuroblastoma, which supports our results indicating a more aggressive disease in the SS group." (PMID 33245713, 2020). "Both LGR5 and HOXD10 were associated with cancer cell proliferation and tumor aggressiveness in neuroblastoma." (PMID 33245713, 2020). "In this study, we show that individual induction of HOXD8, HOXD9, HOXD10 or HOXD12 in neuroblastoma cells is able to recapitulate RA-induced differentiation phenotype." (PMID 22879880, 2012). "Together, these findings demonstrate distinct functions of HOXD proteins in regulation of neuroblastoma cell proliferation, with only HOXD3, HOXD8, HOXD9, HOXD10 and HOXD12 proteins being able to recapitulate the G1 arrest phenotype induced by RA." (PMID 22879880, 2012). "Furthermore, qRT-PCR confirmed a significantly lower expression of HOXD10, HOXD11 and HOXD13 in neuroblastoma and osteosarcoma." (PMID 27363011, 2016). "Interestingly, only HOXD10, HOXD11 and HOXD13 of the homeobox loci, normally involved in bone formation and ossification pattern of bones, were significantly up-regulated in ES in comparison to neuroblastoma, normal and fetal tissue." (PMID 27363011, 2016). "Notably, the four human HOXD proteins (HOXD8, HOXD9, HOXD10, HOXD12) with both anti-growth and differentiation-inducing activities in neuroblastoma cells correspond to the Drosophila Hox proteins abd-A (HOXD8) and Abd-B (HOXD9, HOXD10, HOX12) that are responsible for specifying the abdomen." (PMID 22879880, 2012).
pancreatic cancer (3 papers, 2022 to 2024). "In a similar finding as for the MMPs, the only reported tumour suppressor function for a HOX gene involving apoptosis acts on a different target; HOXD10 has been shown to block the expression of the anti‐apoptotic gene survivin in pancreatic cancer." (PMID 35080776, 2022).
rheumatoid arthritis (3 papers, 2023 to 2024). A chronic, systemic autoimmune disorder characterized by inflammation in the synovial membranes and articular surfaces. "In addition, increasing evidence has proved that HOXD10 is involved in inflammatory effects in diverse diseases such as rheumatoid arthritis and Alzheimer’s disease." (PMID 38756247, 2024). "Previous study illustrated that HOXD10 depletion down-regulates the activity and migration of RAFLS in rheumatoid arthritis and ameliorates arthritis by inhibiting p38/c-Jun signaling pathway." (PMID 38756247, 2024).
cervical cancer (2 papers, 2017 to 2023). A primary or metastatic malignant neoplasm involving the cervix. "However, the reduction of HOTAIR expression among the cervical cancers could be responsible for the loss of such gene silencing and hence HOXD10 upregulation, which demanded further validation." (PMID 28402266, 2017). "The increased HOXD10 expression among the cervical cancer cases recorded in our previous report, correlated negatively with lncRNA HOTAIR expression." (PMID 28402266, 2017). "On the other hand, in our earlier report, we interpreted the increased HOXD10 expression in cervical cancer cases to be the result of E7-dependent inactivation of HOTAIR mediated gene silencing through PRC2-LSD1 complex." (PMID 28402266, 2017).
congenital vertical talus (2 papers, 2018). Isolated congenital vertical talus (CVT) is a rare pedal deformity recognizable at birth by a dislocation of the talonavicular joint, resulting in a characteristic radiographic near-vertical orientation of the talus. "Interestingly, HOXD10 mutations were previously identified in two families with vertical talus, which strongly supports a role of homeobox gene mutations in the etiology of isolated vertical talus." (PMID 30134936, 2018). "HOXD10 functions as a transcription factor and is related to some disease such as Wilm's tumor, congenital vertical talus and Charcot-Marie-Tooth disease." (PMID 30115812, 2018).
diffuse large B-cell lymphoma (2 papers, 2018 to 2021). "miR-224, one member of miRNAs, has been identified as a biomarker that predicts the treatment response to chemotherapy in diffuse large B-cell lymphoma (DLBCL) patients, and also as an oncogene in NSCLC by targeting homeobox protein hox-d10 (HOXD10)." (PMID 33819917, 2021).
esophageal cancer (2 papers, 2014 to 2018). A primary or metastatic malignant neoplasm involving the esophagus. "HOXD10 has been reported as a direct target of miR-10b in human breast and esophageal cancers and its downregulation in GBM has been shown to affect cell invasion, tumor proliferation, and migration." (PMID 29765554, 2018).
gastric tumors (2 papers, 2015 to 2022). "miR-10b can stimulate the upregulation of RhoC and AKT phosphorylation through targeting HOXD10, thus promoting cell invasion in gastric tumors." (PMID 26311318, 2015).
invasive ductal carcinoma (2 papers, 2014 to 2021).
lung adenocarcinoma (2 papers, 2019 to 2024). A carcinoma that arises from the lung and is characterized by the presence of malignant glandular epithelial cells. "However, expression of HOXD10 increased when antagonists were added and progression to metastasis of lung adenocarcinoma was inhibited." (PMID 39759007, 2024).
Wilms tumor (2 papers, 2017 to 2018). An embryonal neoplasm characterized by the presence of epithelial, mesenchymal, and blastema components. "A mutation in HOXD10 has been found to be a causative variant in Wilm’s tumor (a pediatric renal tumor), further supporting its role in the kidney’s cell cycle." (PMID 28335481, 2017).
acute kidney injury (1 paper, 2017). Sudden and sustained deterioration of the kidney function characterized by decreased glomerular filtration rate, increased serum creatinine or oliguria. "The genes TGIF1 and HOXD10 are rarely considered in the pathogenesis of acute kidney injury." (PMID 28335481, 2017).
Alzheimer disease (1 paper, 2024). A progressive, neurodegenerative disease characterized by loss of function and death of nerve cells in several areas of the brain leading to loss of cognitive function such as memory and language. "HOXD10 overexpression suppresses neuronal apoptosis, inflammatory response, and oxidative stress, thereby restoring cognitive deficits in Alzheimer’s disease mice." (PMID 38756247, 2024).
cholangiocellular carcinoma (1 paper, 2019). "MAPK pathway is over expressed and associated with functional mutation of HOXD10 gene in human cholangiocellular carcinoma and ovarian cancer." (PMID 30683109, 2019). "The same result can be seen in human cholangiocellular carcinoma, the HOXD10 expression was pretty high in well-differentiated cancerous tissues (25/28, 89.3%), while the HOXD10 was lowly expressed in well-differentiated cancerous tissues (25/28, 89.3%)." (PMID 30683109, 2019).
clear cell ovarian cancer (1 paper, 2024). "We previously found that HOXD10 drives the expression of a microRNA (miRNA) associated with endometrioid ovarian cancer and clear cell ovarian cancer." (PMID 38356716, 2024).
clubfoot (1 paper, 2024). The most common congenital deformation of the foot, occurring in 1 of 1,000 live births. "Initially, genes associatedwith clubfoot (PITX1, TBX4, HOXA9, HOXD10, HOXD12,HOXD13, HOXA9, TPM1, TPM2, COL9A1, FLNB, CASP8,CASP10, UTX, CHD1, RIPPLY2, CAND2, WNT7) werescreened for potential variants." (PMID 38952703, 2024).
colitis (1 paper, 2024). Inflammation of the colon. "Overall, these findings uncovered that HOXD10 might ameliorate DSS-induced colitis by mediating Rho/ROCK/MMPs axis." (PMID 38756247, 2024).
colorectal tumors (1 paper, 2019). "To investigate the function of HOXD10 in colorectal tumors, we transfected CRC cells with a HOXD10 vector or empty vector and then confirmed the level of mRNA." (PMID 30683109, 2019).
cystic teratoma (1 paper, 2024). "The most interesting findings of this study are amplifications of EVX2, HOXD13, HOXD12, HOXD11, HOXD10, and HOXD9 on a 41.6 kb segment of 2q31.1 in all nine mature cystic teratomas." (PMID 38907278, 2024). "In summary, amplifications of EVX2, HOXD13, HOXD12, HOXD11, HOXD10, and HOXD9 on 2q31.1, NDUFV1 on 11q13.2, and RPL10, SNORA70, DNASE1L1, TAZ, ATP6AP1, and GDI1 on Xq28 were found in all nine mature cystic teratomas in this study." (PMID 38907278, 2024).
liver cancer (1 paper, 2025). An epithelial or non-epithelial malignant neoplasm that arises from the liver. "Here, we found that KLX increased HOXD10 levels, which in turn promoted ZBP1 transcription and inhibited liver cancer cell growth." (PMID 40148674, 2025).
melanoma (1 paper, 2020). A malignant, usually aggressive tumor composed of atypical, neoplastic melanocytes. "In conclusion, we showed that the oncogenic activity of miR-378a-5p in melanoma functions includes two regulatory events: an increase of in vitro cell invasion, migration and VM through HOXD10/uPAR axis, and an increase of in vitro and in vivo angiogenesis through VEGF." (PMID 32060259, 2020).
metastatic prostate carcinoma (1 paper, 2016). A carcinoma that arises from the prostate gland and has spread to other anatomic sites. "Among these elements are two TFs (PGR and HOXD10) in the primary and three TFs (STAT3, JUN and JUNB) in the metastatic prostate cancer network." (PMID 28005952, 2016).
metastatic tumor (1 paper, 2016). "Among them, HOXD10 and PGR are specific to primary tumor, while STAT3, JUN and JUNB are associated to metastatic tumor based on our integrative regulatory network and survival analysis." (PMID 28005952, 2016).
mouth neoplasms (1 paper, 2022). "Two other posterior HOX genes, HOXD10, and HOXD11 were shown to be associated with the mouth neoplasm based on the semantic analysis performed using DO." (PMID 35710803, 2022).
papillary thyroid cancer (1 paper, 2019). "Previous studies have showed that HOXD10 which was aberrantly hypermethylated in papillary thyroid cancer may act as a tumor suppressor." (PMID 30683109, 2019).
prostate tumor (1 paper, 2016). "Based on the regulatory network analysis of primary prostate tumor, HOXD10, BCL2 and PGR are 3 key elements in the network." (PMID 28005952, 2016). "Survival curves based on the key molecules (HOXD10 and PGR) in primary prostate tumors shows significance differences between the high expression and low expression groups (P-value < 0.05)." (PMID 28005952, 2016).
tumor (97 papers, 2009 to 2025). "Firstly, we found that HOXD10 was frequently methylated in CRC and that overmethylated HOXD10 was associated with tumor stage and lymph node metastasis." (PMID 34790580, 2021). "Among them, three genes, HOXD10 (11/472), Sprouty2 (73/472), and Marcks (332/472), were implicated in tumor invasion." (PMID 30603114, 2018). "HOXD10 methylation was significantly associated with vessel cancerous embolus, tumor cell differentiation, and the 3-year overall survival rate (all P < 0.05)." (PMID 29075359, 2017). "HOXD10 methylation was associated with vessel cancerous embolus, tumor cell differentiation, and the 3-year survival rate." (PMID 29075359, 2017). "Methylation of HOXD10 was associated with vessel cancerous embolus, tumor cell differentiation, and the 3-year survival rate in human HCC." (PMID 29075359, 2017). "miR-10b inhibits the translation of mRNA encoding HOXD10, which modulates many genes that promote invasion, migration, extracellular matrix remodeling and tumor progression." (PMID 25236186, 2014). "Notably, both FLG-AS1 and HOXD10 exhibit anti-tumor properties in ESCC, while miR-23a-3p is implicated in carcinogenesis." (PMID 40462237, 2025). "Tumor-derived exosomes often carry miRNAs that suppress tumor suppressor genes like HOXD10, promoting metastasis." (PMID 41440381, 2025). "In vitro overexpression of HOXD10 resulted in the same impact on proliferation and apoptosis, therefore suggesting that HOXD10 functions as a tumor suppressor and, thus, hypermethylation of this gene allows for CRC progression." (PMID 39858044, 2025). "Overall, these data implicate HOXD10 as a tumor suppressor in GBM and suggest that the miR-23a–HOXD10 regulatory axis plays a key role in the regulation of EMT in this cancer type." (PMID 39858044, 2025). "By downregulating HOXD10, a gene known for its tumor-suppressive functions, miR-10b facilitates tumor cell migration and invasion, thereby contributing to the aggressive nature of GB." (PMID 40896358, 2025). "Its upregulation in gastric cancer tissues and cell lines leads to the suppression of HOXD10, a tumor suppressor gene, resulting in increased expression of RHOC, a gene linked to enhanced metastatic potential." (PMID 39796267, 2025). "It has been reported that HOXD10 is a vital tumor suppressor that inhibits cells migration in various cancers." (PMID 38756247, 2024). "DEG analyses revealed the genes contributing to RFS and related to SUVmax (PSG5, TFF3, SOX2, SLC5A5, and SLC5A7) and tumor size (HOXD10, IFNA1, and FER1L6)." (PMID 38745021, 2024). "For example, HOXD10 is identified as a tumor suppressor gene to inhibit cancer development and enhance apoptosis in human cholangiocarcinoma." (PMID 38756247, 2024). "EVX1 and HOXD10 are key developmental genes, playing crucial roles in cellular differentiation and tumor suppression." (PMID 39649173, 2024). "HOXD10 is an inhibitor of tumor metastasis, and its expression is significantly downregulated in several types of carcinomas, such as prostate cancer, breast cancer, and liver cancer." (PMID 34825321, 2022). "On this basis, the majority of HOX genes would appear to have a pro‐oncogenic function, with the notable exception of HOXD10, which acts exclusively as a tumour suppressor." (PMID 35080776, 2022). "Immunohistochemistry for HOXD10 showed that in lymph node metastases the signal was significantly reduced (p<0.05) compared to that in the primary tumor." (PMID 36387245, 2022).